PRDM2 (PR/SET domain 2)
Description:
S-adenosyl-L-methionine-dependent histone methyltransferase that specifically methylates 'Lys-9' of histone H3. May function as a DNA-binding transcription factor. Binds to the macrophage-specific TPA-responsive element (MTE) of the HMOX1 (heme oxygenase 1) gene and may act as a transcriptional activator of this gene.
Synonyms: KMT8; RIZ; RIZ1; RIZ2; MTB-ZF; HUMHOXY1; KMT8A
Tractability: PROTAC: UniProt records ubiquitination sites on it; ubiquitination databases record sites on it; its protein half-life has been measured.
Target class: Enzyme; Transferase
Gene: Protein-coding gene on chromosome 1 (13,700,188 to 13,825,079, forward strand). Ensembl gene ENSG00000116731.
Subcellular location: Nucleus
Subcellular location (Human Protein Atlas): Golgi apparatus; Nucleoplasm
Gene Ontology:
Molecular function: DNA-binding transcription activator activity, RNA polymerase II-specific; DNA-binding transcription repressor activity, RNA polymerase II-specific; histone H3K9 methyltransferase activity; protein binding; RNA polymerase II transcription regulatory region sequence-specific DNA binding; sequence-specific DNA binding; DNA-binding transcription factor activity; DNA-binding transcription factor activity, RNA polymerase II-specific; zinc ion binding; histone H3K9 trimethyltransferase activity; histone methyltransferase activity
Biological process: negative regulation of transcription by RNA polymerase II; positive regulation of transcription by RNA polymerase II; regulation of DNA-templated transcription; regulation of transcription by RNA polymerase II; chromatin remodeling
Cellular component: nucleoplasm; nucleus
Genetic constraint (gnomAD): Loss-of-function variants: 25 observed, 117.48 expected, observed/expected ratio (o/e) 0.21, 90% interval 0.15 to 0.3. The upper end of that interval is the gene's LOEUF score, 0.3, which puts it in group 1 of 6, group 1 being the genes least tolerant of losing a copy. Missense variants: 1,937 observed, 2,089.1 expected, observed/expected ratio (o/e) 0.93, 90% interval 0.89 to 0.96. Synonymous variants: 843 observed, 780.99 expected, observed/expected ratio (o/e) 1.08, 90% interval 1.02 to 1.14.
Homologues: Orthologues: chimpanzee PRDM2 (99% identical), macaque PRDM2 (98% identical), dog PRDM2 (88% identical), guinea pig PRDM2 (87% identical), pig PRDM2 (85% identical), mouse Prdm2 (84% identical), rat Prdm2 (84% identical), rabbit PRDM2 (74% identical), tropical clawed frog prdm2 (56% identical), zebrafish prdm2b (41% identical). Paralogues in human: ZNF592 (10% identical), ZNF687 (10% identical), WIZ (7% identical), ZNF407 (7% identical), ZNF527 (6% identical), ZKSCAN7 (6% identical), ZBTB17 (6% identical), ZNF287 (6% identical), ZNF852 (6% identical), ZNF214 (5% identical), ZNF17 (5% identical), ZNF398 (5% identical), and 38 more.
Diseases named in the same sentence as PRDM2 in open-access papers:
PRDM2 is named in the same sentence as 86 diseases in open-access papers, as found by Europe PMC text mining. Sharing a sentence is not in itself a finding about the gene and the disease. The quoted sentences say what the papers report.
breast carcinoma (15 papers, 2001 to 2025). "Changes to chromosome 1p36, on which PRDM2 is located, are also associated with numerous types of cancer, including breast cancer, ovarian cancer, liver cancer, colorectal cancer, chronic myeloid leukemia, melanoma, chromaffin tumor and neuroblastoma." (PMID 25884948, 2015). "For example, PRDM2 (RIZ1) has been reported to have tumor‐suppressive activities in a variety of tumors, and its expression is down‐regulated in the breast cancer and liver cancer due to its promoter methylation." (PMID 27485778, 2016). "PCR and subsequent agarose gel electrophoresis (AGE) results showed that AEP/tDDX3X-C enhanced the ES of PRDM2 exon 2, ARRB1 exon 13, and NCOR2 exon 21 in both glioma and breast cancer cells." (PMID 37988165, 2023). "Furthermore in normal and cancer germ cell lines, PRDM2 binds estradiol receptor α (ERα) and influences proliferation, survival and apoptosis, as previously reported using MCF-7 breast cancer cell line, suggesting a potential tumor-suppressor role in TGCT formation." (PMID 27983647, 2016).
colorectal cancer (11 papers, 2013 to 2023). A primary or metastatic malignant neoplasm that affects the colon or rectum. "PRDM2 is frequently inactivated by mutations in colorectal cancer cell lines and in relapsed bladder cancer." (PMID 29352181, 2018). "We then engineered isogenic cell systems where the PRDM2 c.4467delA mutation in human HCT116 colorectal cancer cells was corrected to wild-type by genome editing." (PMID 29228717, 2017). "Consistently, our Exome- and RNA-Seq public datasets available at The Cancer Genome Atlas (TCGA) portal analysis revealed that a subset of PRDMs, including PRDM2, are frequently mutated and/or transcriptionally deregulated in certain tumor types, such as colorectal cancer (CRC)." (PMID 37853459, 2023). "Additionally, a recent study identified a driver PRDM2 mutation in MSI colorectal cancer." (PMID 30347759, 2018). "PRDM2 is a member of the histone methyltransferase superfamily, interacts with the RB protein, and is proposed as a tumor suppressor in colorectal cancer." (PMID 23717195, 2013). "As for PRDM2 gene, a mononucleotide repeat (A7) in exon 8 of MECOM coding sequences was found to be a target for frameshift mutation (loss-of-function mutation) in colorectal cancers with MIN." (PMID 32290321, 2020). "Additionally, the mutational frequency was >10% in 8 other TSGs in colorectal cancer: FAT4 (19%), TOPORS (15%), PPP2CB (13%), RASL11A (13%), PCDH9 (12%), PRDM2 (12%), LIFR (11%) and TGFBR2 (11%)." (PMID 26590405, 2016).
lung carcinoma (9 papers, 2010 to 2025). "Furthermore, in addition to those genes previously associated with lung cancer, TSGs and oncogenes known to be deregulated in other cancer types–such as PRDM2 and SIAH2, respectively – were also altered at the genetic, epigenetic and gene expression levels." (PMID 22629454, 2012). "In line with previous studies, our results demonstrated that PRDM2 downregulation occurs in ovarian cancer, esophageal squamous cell carcinoma, hepatoma and lung cancer." (PMID 32391195, 2020). "Studies have shown that the PRDM2, PRDM5, and PRDM16 promoters in lung cancer cells are methylated, resulting in suppressed expression." (PMID 39468462, 2024).
glioma (8 papers, 2013 to 2025). A benign or malignant brain and spinal cord tumor that arises from glial cells (astrocytes, oligodendrocytes, ependymal cells). "The variant rs35042965 is an intergenic variant downstream of the PRDM2 gene and is protective against male risk of glioma (OR = 0.81; P = 1.54 × 10−6)." (PMID 39387520, 2024). "Two of the 11 regions, 16p13.3 containing RBFOX1 and 1p36.21 containing PRDM2, were significantly associated with female and male glioma risk respectively, based on the results of the meta-analysis." (PMID 39387520, 2024). "The GBJ set-based analysis of the meta-analysis results found two of the 11 regions (16p13.3 containing RBFOX1 and 1p36.21 containing PRDM2) were significantly associated with female and male glioma risks, respectively, after adjusting for multiple testing (P16p13.3 = 0.003; P1p36.21 = 0.002)." (PMID 39387520, 2024). "Of the 11 candidate susceptibility regions, two regions were consistently associated with glioma risk across multiple studies and methods, 16p13.3 an intronic region of the RBFOX1 gene, and 1p36.21 containing the genes PDPN and PRDM2." (PMID 39387520, 2024). "Moreover, a significant reduction of PRDM2 expression was observed in high-grade gliomas, and forced expression of PRDM2 in glioma cell lines inhibits cell proliferation and increases apoptosis." (PMID 30347759, 2018). "In summary, the hypermethylation of the PRDM2/RIZ gene promoter is also one of the pathogenic mechanisms of neurological diseases, such as meningiomas and gliomas, suggesting that PRDM2/RIZ may be one of the targets for the diagnosis and prevention of neurological diseases." (PMID 40867614, 2025). "Several genes down-regulated in BAT such as PRDM2, TCF7L2, RB1CC1, ATP2A2 are involved in the pathogenesis of other type of cancers, but not in gliomas." (PMID 23472076, 2013).
hepatocellular carcinoma (7 papers, 2001 to 2025). A malignant tumor that arises from hepatocytes. "The distal short arm of human chromosome 1 (1p36) is usually altered in primary hepatocellular carcinomas and cell lines, whereas the PRDM2 gene is in this region." (PMID 40867614, 2025). "Furthermore, in a meta-analysis that found a total of 22 genes methylated in hepatocellular carcinoma, PRDM2 was one of the genes with the most significant result and is on par with the well-known APC and p16." (PMID 32391195, 2020). "Therefore, PRDM2 and its isoforms may serve as potential biomarkers for the diagnosis and treatment of hepatocellular carcinoma." (PMID 40867614, 2025). "The RIZ (PRDM2) locus commonly undergoes loss of heterozygosity (LOH) and maps within the minimal deleted region on 1p36 in hepatocellular carcinoma (HCC)." (PMID 11259086, 2001). "The PR domain of PRDM2/RIZ1 itself showed growth inhibitory and anticancer activities; indeed, it increased cell death when transfected in human hepatoma HuH7 cells." (PMID 32290321, 2020).
melanoma (7 papers, 2013 to 2025). A malignant, usually aggressive tumor composed of atypical, neoplastic melanocytes. "The gene PRDM2 showed a mutation pattern of mutual exclusivity with CDKN2A and is of particular interest since PRDM2 is a binding partner of RB1, a well‐established melanoma driver." (PMID 36219477, 2023).
meningioma (7 papers, 2016 to 2025). A generally slow growing tumor attached to the dura mater. "More recently, a study demonstrated that PRDM2/RIZ1 could lead to G2/M arrest of meningioma cells by acting on the expression of the checkpoint protein UbcH10, an important member of the ubiquitin-conjugating enzymes family, through c-Myc degradation." (PMID 32290321, 2020).
diffuse large B-cell lymphoma (4 papers, 2009 to 2023). "Loss of heterozygosity, promoter hypermethylation or PRDM2 gene mutations have been observed in several human cancer types, including Diffuse Large B-Cell Lymphoma (DLBCL)." (PMID 36964555, 2023).
alcohol dependence (3 papers, 2017 to 2024). Physical and psychological dependence on alcohol. "We previously found that downregulation of the histone methyltransferase PR containing domain 2 (PRDM2), by a history of alcohol dependence, was associated with increased stress responses." (PMID 36127428, 2022). "Intriguingly, alcohol-dependent rats exhibit downregulated PRDM2 expression following a history of alcohol dependence." (PMID 39202552, 2024). "Finally, given our prior findings that alcohol dependence down-regulates dmPFC PRDM2 expression, we provide a candidate mechanism for the extensive co-morbidity of alcohol use and anxiety disorders." (PMID 36127428, 2022). "PFC viral vector mediated reduction of Prdm2 in non-dependent rats increased ethanol drinking even in the presence of quinine adulteration displaying phenotypes characteristics of alcohol dependence." (PMID 29018328, 2017).
Obesity (3 papers, 2018 to 2025). Accumulation of substantial excess body fat. "In our results, we found that PRDM2 is downregulated in NASH and depression datasets whereas it is upregulated in diabetes and obesity." (PMID 34833079, 2021). "Additionally, we investigated five genes, PRDM2, CXCL1, PHLDA1, DIDO1, CDA, which were commonly expressed in all datasets including depression, obesity, diabetes, and NASH." (PMID 34833079, 2021).
allergic disease (2 papers, 2022 to 2023). An immune response that occurs following re-exposure to an innocuous antigen, and that requires the presence of existing antibodies against that antigen. "Noteworthy, a recent meta-analysis of multi-trait genome-wide association studies identified PRDM2 as a locus associated with six autoimmune and allergic diseases thus suggesting the implication of this gene." (PMID 36964555, 2023). "Our study newly identified six loci associated with allergic diseases (MIIP, CXCR4, SCML4, CYP1B1, ICOS and LINC00824) and four pleiotropic loci associated with both autoimmune and allergic diseases (PRDM2, G3BP1, HBS1L and POU2AF1)." (PMID 35753705, 2022). "We identified four loci shared between the six autoimmune and allergic diseases (rs10803431 at PRDM2, OR=1.07, p=2.3×10−8, rs2053062 at G3BP1, OR=0.90, p=2.9×10−8, rs2210366 at HBS1L, OR=1.07, p=2.5×10−8 in Japanese and rs4529910 at POU2AF1, OR=0.96, p=1.9×10−10 across ancestries)." (PMID 35753705, 2022).
bladder cancer (2 papers, 2016 to 2023). "Taken together, the mutations of MLL, EP400 and PRDM2 may be involved in bladder carcinoma relapse." (PMID 26625313, 2016). "After discovery and confirmation, five genes MLL, EP400, PRDM2, ANK3 and CHD5 significantly correlated with the recurrence of bladder cancer." (PMID 26625313, 2016). "Additionally, the contribution of specific alterations of EP400, PRDM2, ANK3 and CHD5 to bladder carcinoma recurrence should also be further investigated." (PMID 26625313, 2016). "Five of the 26 SMGs had not been reported as SMGs in bladder cancer in previous studies: CDKN1B (1.2%), ITK (1.8%), PRDM2 (3.1%), FOXA1 (2.7%), and BAP1 (1.8%)." (PMID 36495164, 2023).
monocytic leukemia (2 papers, 2013 to 2025). "Afterwards, a PRDM2 variant, named MTE-binding protein ZF type (MTB-Zf, UniProt ID: Q13029-2), has been isolated from a human monocytic leukemia cell line cDNA expression library." (PMID 40867614, 2025).
parathyroid adenoma (2 papers, 2020 to 2025). "Genome-wide methylation profiling reveals RIZ1 (PRDM2) silencing via promoter hypermethylation in 36% of sporadic parathyroid adenomas, where its loss dysregulates cell cycle by modulating histone methyltransferase activity." (PMID 41210508, 2025).
parathyroid tumors (2 papers, 2024 to 2025). "Among them, PRDM2 mediates the progression of parathyroid tumors and lactinomas, but there are fewer related studies with their limitations to be added." (PMID 40867614, 2025).
retinoblastoma (2 papers, 2015 to 2025). A malignant tumor that originates in the nuclear layer of the retina. "Discovered to have the ability to bind retinoblastoma in the mid-1990s, PRDM2 was assumed to play a role in neuronal development." (PMID 40867614, 2025).
somatotroph adenoma (2 papers, 2023 to 2025). "PRDM2 (PR Domain Zinc Finger Protein 2) is a tumor suppressor gene associated with somatotroph adenomas." (PMID 40362297, 2025). "The absence of PRDM2 is likely to be involved in the tumorigenesis of somatotroph adenomas by regulating c-Myc oncogene, which is involved in cellular metabolism and proliferation." (PMID 40362297, 2025).
Anxiety (1 paper, 2022). Intense feelings of nervousness, tension, or panic often arise in response to interpersonal stresses. "We found that Prdm2 KD in the dmPFC-BLA neurons modulated the expression of genes that have been associated with fear conditioning, anxiety, emotional behavior, and memory." (PMID 36127428, 2022). "The effect of Prdm2 KD on anxiety-like behavior was also tested." (PMID 36127428, 2022). "However, this was not significant, suggesting that Prdm2 does not robustly affect innate anxiety-like behaviors (scrambled: n = 20 and Prdm2 KD n = 20)." (PMID 36127428, 2022).
autoimmune disease (1 paper, 2023). A disorder resulting from loss of function or tissue destruction of an organ or multiple organs, arising from humoral or cellular immune responses of the individual to their own tissue constituents. "Thus, the whole knowledge of the transcription regulation mechanisms involving PRDM1 and PRDM2 genes in the immune biology can provide the molecular bases for the application of these new strategies to the autoimmune diseases." (PMID 36964555, 2023).
colon adenocarcinoma (1 paper, 2023). "We first evaluated the expression of the different PRDM2 transcripts by in silico analysis of TCGA-COAD (colon adenocarcinoma) datasets on GEPIA2." (PMID 37853459, 2023).
gastric carcinoma (1 paper, 2015). A carcinoma that arises from epithelial cells of the stomach. "Moreover, inactivation of the PRDM2 gene by promoter hypermethylation has been reported in breast, liver, and gastric carcinomas." (PMID 25884948, 2015).
malignant mesothelioma (1 paper, 2025). A malignant neoplasm of the pleura or peritoneum, arising from mesothelial cells. "Whole-genome sequencing of blood and cancerous tissues from patients with malignant mesothelioma of the vaginal testicular membrane reveals mutations in the PRDM2 gene, suggesting that PRDM2 may serve as a target for the development of malignant mesothelioma of the vaginal testicular membrane." (PMID 40867614, 2025).
multiple myeloma (1 paper, 2024). "PRDM2, a member of the histone/protein methyltransferase superfamily, is a tumour suppressor gene, and its expression is downregulated in some solid tumours, such as multiple myeloma and pituitary adenoma." (PMID 38553479, 2024).
osteoporosis (1 paper, 2025). A condition of reduced bone mass, with decreased cortical thickness and a decrease in the number and size of the trabeculae of cancellous bone (but normal chemical composition), resulting in increased fracture incidence. "Additionally, estrogen combined with PRDM2 plays a role in osteoporosis and Parkinson’s disease." (PMID 40867614, 2025).
Parkinson disease (1 paper, 2025). A progressive degenerative disorder of the central nervous system characterized by loss of dopamine producing neurons in the substantia nigra and the presence of Lewy bodies in the substantia nigra and locus coeruleus. "The results confirm the association of the PRDM2 variant with susceptibility to Parkinson’s disease, which is particularly prevalent in women." (PMID 40867614, 2025).
prolactinomas (1 paper, 2025). "Additionally, molecular markers including DRD2 gene variants, altered expression levels of PRDM2, Filamin A, or PRB3, and dysregulated TGF-β1/Smad3 signaling pathways offer insights into the molecular pathogenesis of aggressive prolactinomas." (PMID 41013821, 2025).
psoriasis (1 paper, 2025). An autoimmune condition characterized by red, well-delineated plaques with silvery scales that are usually on the extensor surfaces and scalp. "Abnormal expressions of proteins like MECOM and PRDM2 further indicate their significance in immune modulation and stem cell functions, likely to influence the pathogenesis of psoriasis." (PMID 40650108, 2025).
stress-related disorder (1 paper, 2022). Stress-related disorders are mental health disorders that are a result of an atypical response to both short and long-term anxiety due to physical, mental, or emotional stress. "This study also provides the first set of evidence for a role of PRDM2 in stress-related disorders." (PMID 36127428, 2022).
thymoma (1 paper, 2023). A neoplasm arising from the epithelial cells of the thymus. "Specifically, we measured the Spearman correlation coefficient R to evaluate the expression correlation of PRDM1, PRDM2 and their main transcripts on three datasets from The Cancer Genome Atlas (TCGA) and Genotype-Tissue Expression (GTEx): whole blood, thymoma normal and EBV-transformed lymphocytes." (PMID 36964555, 2023).
urinary tract tumors (1 paper, 2025). "Firstly, the current research on PRDM2 in the urinary and circulatory system diseases is still blank, and its specific functions in cardiovascular regulation, kidney development, and urinary tract tumors have not been systematically clarified, indicating a broad exploration space in these areas." (PMID 40867614, 2025).